AR (androgen receptor)
Diseases named in the same sentence as AR in open-access papers (continued):
Sharing a sentence is not in itself a finding about the gene and the disease.
tumor (continued). "Although this seems counterintuitive, increased expression of UGT2B17 induced by AR-SV could be part of a coordinated response to make the tumor remain dependent on AR signaling in the absence of ligand." (PMID 35582223, 2020). "Furthermore, it would be interesting to evaluate the prognostic value of AR‐pathway activity and SRD5A1 expression, as the survival differences may also be a result of a more indolent (well‐differentiated) tumor." (PMID 31745978, 2020). "Thus, AR-mediated AMPK activation could potentially function to avoid energy crisis and promote tumor growth." (PMID 32630372, 2020). "High AR expression was a significant favorable prognostic factor for overall survival in all of the subjects and subgroups with a tumor size of ≤2 cm, a negative node, a positive ER, a negative HER2, a histologic grade 1 or 2, a body mass index ≤25 kg/m2, a lumpectomy, and endocrine therapy." (PMID 32290220, 2020). "Moreover, testosterone supplementation resulted in strong AR-pathway activation in PC346C-DCC-K tumours as exemplified by increased prostate-specific antigen production, AR nuclear localisation, AR target gene expression and tumour cell proliferation." (PMID 32989230, 2020). "Furthermore, the effect of the isolated metabolites on AR-regulated transcription was evaluated in vitro in human tumor and non-cancerous cells, with compound 11 exhibiting the strongest inhibition of AR at 10 μM." (PMID 33322046, 2020). "Moreover, AR silencing in three cell lines representative of the luminal androgen receptor subtype (including MDA-MB-453) significantly reduced cell growth and colony formation, indicating that AR is partly responsible for tumor cell viability/survival." (PMID 32429078, 2020). "However, the response of the hypothalamic–pituitary–gonadal axis, several cytokines, and gastrocnemius transcriptome to androgen, along with no obvious effects of tumor burden on AR mRNA or protein, suggests global AR blockade is unlikely." (PMID 31930715, 2020). "Neither tumor nor treatment had a significant impact on AR mRNA." (PMID 31930715, 2020). "In this study the absence of HIF1a and endogenous androgen in vivo resulted in regression of tumor growth but HIF1a signaling could restore tumor growth in the absence of AR signaling." (PMID 32450824, 2020). "Interestingly, combined treatment with SP-2509 and JQ1 synergistically inhibits growth in castration-resistant PCa cells and inhibits tumor invasion in low/negative AR-expressing PCa." (PMID 31901895, 2020). "Additionally, RNAseq did not identify differential expression of the AR or NCOA3 in canine OSA relative to non-tumor bone tissue." (PMID 32854182, 2020). "Then, the DHT–AR complex specifically acts on AR response elements and promotes the transcription of the downstream target genes, such as Wnt/β-catenin signaling pathway, CD24, vascular endothelial growth factor (VEGF), etc., which enhance tumor proliferation, metastasis, and angiogenesis." (PMID 32983992, 2020). "Although AR protein expression was in general high, one tumor lacked AR protein expression." (PMID 31745978, 2020). "However, increased expression of AR in PCa tumour tissue does not qualify as a biomarker for prognosis and hormonal response, as levels of estrogen receptor do for patients with breast cancer." (PMID 33292167, 2020). "Similarly, treatment of mice bearing AR+/hi LNCaP-AI with two cycles of E7107 (left) and PC3 xenografts with one cycle of E7107 (left) also inhibited tumor growth." (PMID 32350277, 2020). "Additionally among grade 1/2 tumours, AR-positive tumours showed a significantly better OS (p = 0.042) than AR-negative tumours." (PMID 32928183, 2020). "Our previous studies demonstrated that the C-terminal acidic domain (CAD) of TSPX is critical for its tumor suppressor functions, such as suppression of cyclin B/CDK1 phosphorylation activities, degradation of a HBV viral oncoprotein HBx, and inhibition of the androgen receptor (AR) transactivation." (PMID 30863497, 2019).
tumor (continued). "Non-genomic AR signalling also promotes tumour cell survival through the activation of PI3K." (PMID 30832393, 2019). "On the other hand, in athymic nude mice, intra-peritoneal infusion of EGCG suppressed tumor growth and reduced the size of AR-negative androgen-insensitive PC-3 xenografts and androgen-positive androgen-independent LNCaP 104-R1 xenografts, whereas EC, EGC, or ECG did not." (PMID 30621039, 2019). "However, our analysis of the influence of tumor grade score on the AR expression level indicated the absence of any significant difference in the rates of experimental and control groups." (PMID 31582998, 2019). "Together with the fact that tumor heterogeneity was not significantly lower in AR high tumors in the ER-positive BC cohort, the relationship between AR expression and TIL does not follow the dogma that heterogeneous tumor produces neoantigens that attract TILs." (PMID 31151151, 2019). "In conclusion, targeting both genomic and non-genomic activity of AR could lead to the eradication of AR tumor dependency in PCa patients." (PMID 31616657, 2019). "Co-expression of AR with pseudogene ASS1P3 could block its suppression likely by inhibiting interaction between miR-34a-5p and ASS1P3, thus releasing the former to suppress ASS1 to promote the tumor growth." (PMID 31000693, 2019). "AR may function as a tumor suppressor or oncogene, likely dependent on cellular context and the presence or absence of AR-modulating factors." (PMID 31116991, 2019). "Thus, ETS− tumors have comparable AR expression when compared to ETS+ tumors, but rather utilize distinctly different AR-dependent transcriptional programs to sustain tumor growth and survival." (PMID 30367117, 2019). "As the AR+ and AR-KO clonal cells are implanted in the same castrated host, the results also provide the first hint that AR-KO cells possess a competitive advantage over AR+ tumor cells in regenerating tumors in the absence of androgen." (PMID 30190514, 2018). "Even though PAPSS2 is not significantly decreased by CNA, intra-tumor loss of PAPSS2 could favor androgen excess and hyperactivation of AR, which is critical for tumor growth and cancer progression." (PMID 30009155, 2018). "In accordance with clinical research, we found that DHT treatment increased xenograft tumor volume and distant metastasis, while HSP27 knock-down inhibited tumor growth greatly, which indicated that the AR and HSP27 might interact with each other and co-influence the development of MABC." (PMID 29699584, 2018). "Interestingly, in our study, relapses could occur even after a long follow-up in patients with AR + /FOXA1 + tumours, like in patients with ER + /HER2- tumours." (PMID 29880907, 2018). "In our in vitro and in vivo experiments, we found that the AR-independent and heterogeneous characteristics of fibroblasts in PCa tissue could regulate ADT efficacy as measured by tumor volume and Ki67 index, which is related to the decline in serum PSA after ADT." (PMID 30567361, 2018). "While tumor cells can adapt and survive when either single pathway is inhibited, combined inhibition of PI3K/AKT and AR signaling using the PI3K/mTOR inhibitor BEZ235 and the AR antagonist enzalutamide (ENZ) significantly delayed castrate‐resistant LNCaP tumor progression." (PMID 29572264, 2018). "Androgen receptor (AR) antagonists are nonsteroidal antiandrogen agents that bind to ARs and inhibit the androgen-induced activation of these receptors, which ultimately inhibits tumor growth and proliferation." (PMID 28801852, 2017). "Collectively, this body of work suggests that residual AR-negative/low PCSCs may remain after androgen deprivation, potentially repopulating tumors with castrate-resistant tumor cells." (PMID 27741508, 2017). "Testing plasma AR status by ddPCR is affordable and can be widely implemented in clinical laboratories but does not control for plasma DNA tumor content that may introduce a bias." (PMID 28472366, 2017).
tumor (continued). "Our study included as many as 190 TNBCs, although we did not examine the genetic profiles of each AR-positive tumor to determine which of these tumors could be classified into the luminal androgen receptor (LAR) subtype." (PMID 28067809, 2017). "The expression of AR was not correlated with age and tumor stage." (PMID 29261702, 2017). "Inhibitors targeting the AR NTD might be promising candidates for blocking non-genomic AR signals that enhance tumor growth or survival." (PMID 28144231, 2017). "Although inhibition of AR using MDV3100 and radiation treatment each independently inhibited tumor volume growth in these models, the combination of MDV3100 and RT treatment resulted in a significant (p < 0.01) and synergistic decrease in tumor growth compared to RT alone." (PMID 28840192, 2017). "However, the expression of AR was not correlated to patient age, tumor size, node status, stage, and vascular invasion or treatment strategies." (PMID 28915596, 2017). "Interestingly, ailanthone more potently inhibited the growth of AR-positive PCa cells than either AR-negative tumor cell lines or normal prostate cell lines." (PMID 28257652, 2017). "In contrast to previous studies in other tumor types where ING3 was reported to function as a tumor suppressor, we find that ING3 levels are higher in aggressive PCs, and that a high level of ING3 is a prognostic factor predicting poorer survival in patients with low AR levels." (PMID 28511652, 2017). "However, some studies had shown that PSA decline did not indicate tumor cell death, but instead represented AR pathway inhibition and subsequent reduced PSA secretion." (PMID 29285263, 2017). "However, knockdown of FOXA1 resulted in a significant reduction of cellular viability on day 5, suggesting that FOXA1 has essential roles for viability of the ER-positive tumor cell lines, although there were no direct effects on ER and AR activities." (PMID 29137314, 2017). "We hypothesized that similar to metabolic mechanisms that elicit DHT synthesis, which in turn stimulate AR in CRPC, a role for GR in enzalutamide resistance would be accompanied by a tumor metabolic switch that provides sustained tissue cortisol concentrations that enable GR activation." (PMID 28191869, 2017). "TGF-β’s tumor promoting activity may be related to its ability to generate and maintain cancer stem cells, including PCa stem cells, which are AR negative and presumably sensitive to TGF-β." (PMID 27863384, 2016). "Finally, to validate the in vitro cell line and in vivo mouse data, we performed a clinical survey of IHC staining on 72 human RCC samples using antibodies against AR or CD31, the key EC marker during the development of blood vessels that supply nutrition during tumor progression and metastasis." (PMID 27848972, 2016). "This suggests that an in vivo assessment of MDM2 antagonists in combination with conventional AR antagonists or newer agents such as MDV3100 is required, which should result in highly effective tumour regression and may delay or prevent the onset of castrate resistant disease." (PMID 27729622, 2016). "Therefore, patients with AR-negative and p-NF-κB-negative tumor are more likely to respond to CDDP-based chemotherapy." (PMID 27322140, 2016). "Furthermore, in vitro experiments using PC-3, DU-145, 22RV1, and LNCaP cell lines in this study found that CBD decreased androgen receptor expression suggesting that crosstalk between the CBD and androgen signaling pathways may affect tumor growth." (PMID 27774065, 2016). "Indeed, inspection of heatmaps, RNA-seq coverage and splice junction data revealed that tumour C-9A, but not tumour C-9B, expressed an AR mRNA species with a splice junction between exon 3 and a 3′-terminal exon recruited from chromosome 11." (PMID 27897170, 2016). "Indeed, both the AR and c-Myc are commonly increased in human CRPC tumor progression." (PMID 26690121, 2015).
tumor (continued). "The AR was not differentially expressed in either the human tumour samples or the cell line model." (PMID 26553226, 2015). "The primary tumor was signed off as AR positive but the metastasis was negative." (PMID 26552477, 2015). "There was no significant change in MCT2 protein expression between AR blockade (Degarelix) treated and untreated PCa tumours, suggesting that any AR signalling effects on specific SLC16A7/MCT2 isoforms do not impact on total MCT2 protein levels in the context of human PCa tumours." (PMID 26035357, 2015). "Moreover, a similar pattern (AR increased, CCL2 significantly decreased) is observed in metastases from patients who did not receive ADT, supporting the idea that CCL2 is only required at the primary tumor site." (PMID 26327448, 2015). "In support of this concept, an examination of 59 hormone naive and 20 hormone refractory (CRPC) tumors using immunohistochemistry demonstrated a heterogeneous pattern of AR expression in both hormone naive PC and CRPC with approximately 25% of tumor cells being AR negative." (PMID 26593949, 2015). "A negative AR status correlated significantly (p < 0.001) with high tumor grade (G3) (37/120)." (PMID 26552477, 2015). "In the adult prostate, activation of epithelial androgen receptor (AR) by testosterone (T) and 5α-dihydrotestosterone (DHT) is necessary for cell survival and regulation of seminal fluid proteins including prostate specific antigen (PSA), which is used clinically for tumour detection and monitoring." (PMID 25965833, 2015). "Significantly downregulated genes in NHT tumours (DESeq comparison; Benjamini-Hochberg P <0.05) were typically androgen responsive (for example, TMPRSS2, KLK3, BMPR1B, TPD52) or steroidogenesis-related (for example, DHCR24, SCD), consistent with a reduction in androgen receptor activity." (PMID 25155515, 2014). "Furthermore, miR-205 had been reported overexpressed in androgen receptor positive TNBC tumor cells but with low expression in androgen negative TNBC." (PMID 25137071, 2014). "ADT down-regulates the androgen receptor (AR) in the tumor but the response in advanced disease is not permanent, a progression may occur as CRPC." (PMID 25674461, 2014). "The effects of FOXA1 depletion and FOXA1 overexpression on AR-mediated transcription as well as Notch pathway and their impact on EC cell proliferation were examined by qRT-PCR, western blotting, co-immunoprecipitation, ChIP-PCR, MTT, colony-formation, and xenograft tumor–formation assays." (PMID 24512546, 2014). "Although lacking significance, the lack of AR-positive cases in the metastatic counterparts of the tumour samples may indicate that once RCC metastasize from their primary site, their AR expression level becomes even lower." (PMID 28326246, 2014). "Taken together, our results indicate that the combination of Rapamycin/Cl-1040/17-AAG decreases tumor metastasis, most likely via the transcriptional suppression of Slug, which is concomitantly expressed by the activation of the MAPK/ERK, PI3K/Akt/mTOR, and Hsp90/AR." (PMID 24130883, 2013). "In addition, ligands of non-testicular origin (adrenal gland or the tumour cells themselves) or ligand-independent activation can contribute to continued AR signalling." (PMID 23945560, 2013). "Thus, no longer reliant on testicular androgens, AR signalling can resume within the tumour microenvironment, leading to the development of CRPC." (PMID 23573093, 2013). "Notably some CRPC tumors, and individual tumor cells in most patients, show very low or absence of nuclear AR immunostaining, and factors down-stream the AR are not necessarily up-regulated in those cases." (PMID 24244276, 2013). "However, in some patients there is no tumor response, and at progression the AR remains in the nucleus." (PMID 23704919, 2013).
tumor (continued). "A likely mechanism for this tumor-specific effect is that BA inhibited DUB activity specifically in PC but not in normal cells, resulting in increased poly-Ub proteins and enhanced degradation of proliferation and pro-survival proteins such as cyclin D1 and AR by the UPS." (PMID 23424652, 2013). "The fact that Celastrol targets AR-ERG-NF-κB signaling and inhibits human VCaP PCa tumor growth in vivo provides strong support for the proof-of-concept of using Celastrol for T/E fusion expressing PCa, which may benefit more than half of PCa patients who carry T/E fusions in their tumors." (PMID 23554889, 2013). "In addition to these conserved genomic aberrations, new copy number changes were evident, particularly the AR region gain shown in CTCs but not in the primary tumor." (PMID 22373240, 2012). "The gain in AR copy number between tumor tissue obtained at initial diagnosis and CTCs subsequently obtained during the CRPC phase may reflect selective pressures towards amplification of the AR in response to androgen deprivation therapy." (PMID 22373240, 2012). "Its anti-tumor activity may be attributed to mechanisms involving down-regulation of SENP1 that restores SUMOylation and deSUMOyaltion balance and negative regulation of AR and c-Jun expression that inhibits the AR and c-Jun mediated transcription in PCa." (PMID 22666381, 2012). "Reduction of AIB1 and AR level results in inhibition of androgen dependent and androgen-independent tumor cell proliferation through direct control of cell cycle genes, suggesting that AIB1 and AR may play important roles in androgen ablation resistance by controlling cell cycle gene expression." (PMID 22035181, 2011). "Complete lack of AR expression is found only in a small sub-population of CRPC bone metastases, but AR negative tumor cells scattered among the positive are found in most CRPC bone metastases, and thus emphasis the need also for therapies not relying only on a functional AR." (PMID 21552559, 2011). "Furthermore, clinical tumor relapse is determined by PSA recurrence, which may give the impression that the AR pathway has become again fully functional." (PMID 21829708, 2011). "Nevertheless, VN/124-1 alone did not decrease AR levels in the HP-LNCaP tumours." (PMID 20842117, 2010). "To investigate whether the synergy between the AR and Wnt transcriptional activities would lead to accelerated tumor cell growth, we set out to measure the growth of PC3 cells under the conditions of overexpressing the AR alone, Wnt1 alone, or the combination of both." (PMID 18218096, 2008). "Thus, our results led us to consider the existence of a regulation of MMPs/TIMPs expression via AR in the same tumor cells, but without a significant influence in the development of distant metastases." (PMID 18507821, 2008). "However, there is still no clear investigation into AR gene amplification and AR protein expression in hormone-sensitive and hormone-resistant prostate cancer, using paired tumours from the same patient." (PMID 12888829, 2003). "This may lead to a decrease in luminal cells, along with an increase in basal intermediate prostate CSCs and AR-negative PCa cells, which exhibit a high proliferation index and repopulate the tumor through transit to the luminal layer, thus giving rise to CRPC." (PMID 40141159, 2025). "Indeed, immunohistochemistry in TUR specimens showed that patients with AR-positive or Rab27b-positive non-muscle-invasive bladder tumor subsequently undergoing BCG therapy had a significantly higher risk of postoperative disease recurrence, compared to those with AR/Rab27b-negative tumor." (PMID 40486871, 2025). "Notably, the E. mundtii PM10 strain, free from AR genes and virulence factors, showed genomic potential to produce T3PKS and terpene alongside the bacteriocins UViB and enterolysin A. Polyketide synthases have potential applications as anti-infective, anti-tumour and immunosuppressive agents." (PMID 39969280, 2025).